ADORA2A (adenosine A2a receptor)
Diseases named in the same sentence as ADORA2A in open-access papers (continued):
Sharing a sentence is not in itself a finding about the gene and the disease.
cancer (149 papers, 2014 to 2026). A tumor composed of atypical neoplastic, often pleomorphic cells that invade other tissues. "ADORA2A, an immunological checkpoint molecule, has been found to have a high association with the majority of female cancers, including BRCA." (PMID 36911389, 2023). "In this study, we characterized 15 cancer-associated mutations of the human adenosine A2A receptor to study their effects on ligand binding and receptor functions in HEK293T cells." (PMID 35897852, 2022). "For the analysis of 24 immune-inhibiting genes, we found that SERPINH1 expression was highly associated with CD276, TGFBI, VEGFA, HAVCR2, IL10, and ADORA2A in most cancers." (PMID 36105106, 2022). "In itself, LUF7445 may be a probe to explore the added value of covalent antagonists for the adenosine A2A receptor in certain disease states such as cancer immunology, in which high adenosine levels are causative." (PMID 27915383, 2017). "Compared to pharmacological blockade or shRNA-mediated knockdown, CRISPR-Cas9-mediated deletion of the adenosine A2a receptor in CAR T cells improved therapeutic efficacy in preclinical cancer models." (PMID 41181132, 2025). "The adenosine A2A receptor (A2AR) has been identified as a therapeutic target for treating neurodegenerative diseases and cancer." (PMID 39202926, 2024). "Careful IHC analysis of the human NEPC and SCLC samples, which are difficult to obtain, as well as mouse cancer organoids and tissues, demonstrate that ADORA2A is highly expressed in the cancer epithelial cells of NEPC and SCLC." (PMID 38099497, 2023). "Knockdown or inhibition of ADORA2A in NEPC or SCLC cell lines also exerts a profoundly repressive role on cancer cell growth in vitro and in vivo, further revealing the value of ADORA2A as an important drug target." (PMID 38099497, 2023). "The immune checkpoint genes TNFRSF25 and ADORA2A were positively correlated with METTL3 expression in most cancer types." (PMID 36614956, 2022). "Among all the significant associations, CD36 expression was negatively correlated with ADORA2A and LAG3 in multiple cancer types, but positively associated with IDO1, IDO2, and KIR3DL1 in multiple cancers." (PMID 34234847, 2021). "Furthermore, PDE2A expression in most cancers was positively associated with PDCD1, EDNRB, ADORA2A, TGFB1, and especially C10orf54." (PMID 39699377, 2024). "A2AR antagonists block the adenosine A2A receptor and show promise in cancer immunotherapy." (PMID 37891562, 2023). "It is worth emphasizing that we have identified another function of ADORA2A in the metabolic regulation of NE epithelial cancer cells, which extends its functions as a coordinator of neural development in the CNS or as an immunosuppressive checkpoint modulator in the immune system." (PMID 38099497, 2023). "In our study, high ADORA2A expression was independently correlated with high PD-1 transcript expression, suggesting that mitigating the checkpoint effect in some cancers might require a combination of adenosine pathway inhibitors together with anti-PD-1 antibodies." (PMID 38731962, 2024). "Therefore, blockade of ADORA2A not only suppresses the aggressive behavior of NE cancer cells, but may also alleviate the immunosuppressive TME, which together lead to a strong antitumor effect on NE malignancies." (PMID 38099497, 2023). "Apart from CYP1A2 and ADORA2A, other genetic factors can influence CAF’s role in cancer and immunity." (PMID 40650030, 2025). "The adenosine A2A receptor (A2AR) is expressed by stromal, cancer, and immune cells, and suppresses immune activity in response to stress-induced extracellular adenosine accumulation." (PMID 40788962, 2025). "The A2AR (adenosine A2A receptor) knockout and its role in the suppressive TME is a significant area of research in cancer immunotherapy." (PMID 39281684, 2024).
cancer (continued). "The correlation analysis of 24 immunosuppressants indicated that EDNRA was positively correlated with ADORA2A, CSF1R, KDR, TGFB1, and TGFBR1 in cancers, including BLCA, CHOL, ESCA, READ, and STAD." (PMID 39601333, 2024). "The expression of ADORA2A and XBP1 was found to have a significant impact on the survival of most cancer types." (PMID 37627013, 2023). "Our analysis revealed a significant correlation (p < 0.05 between DNMT1 and ADORA2A, IL10RB, and CTLA-4 in certain cancers." (PMID 37628671, 2023). "Molecular correlation analysis showed that USP20 significantly and positively correlated with the expression of multiple immune checkpoints such as ADORA2A and CD160 in a variety of cancers." (PMID 36874086, 2023). "IVM showed that antagonization of adenosine A2a receptor (ADORA2a) signaling improved CTL-target engagement and cancer cell killing." (PMID 37261345, 2023). "And especially, USP28 was significantly correlated with NRP1, CD276, ADORA2A, and TNFSF15 in most cancers." (PMID 37450415, 2023). "Several studies have shown that adenosine suppresses CD8+ T-cells by activating the adenosine A2A receptor (A2AR) and blocking A2AR with selective antagonists results in enhanced anti-cancer immune responses." (PMID 36090975, 2022). "Additionally, USP37 demonstrated a significant positive relationship with ADORA2A, CD160, TNFSF15 and NRP1 across the majority of cancers." (PMID 40926837, 2025). "In regard to outcomes, high ADORA2A expression (unexpectedly) correlated with longer OS from time of advanced/metastatic in our pan-cancer patients, but did not correlate significantly with the outcome (PFS or OS) after immunotherapy." (PMID 38731962, 2024). "Therefore, we propose a new mechanism of ADORA2A-mediated metabolic-epigenetic cascade via the ERK/MYC/PYCR/SIRT6/7 axis in promoting lineage plasticity and resistance to targeted therapy in cancer cells." (PMID 38099497, 2023). "In addition, the genes included in the low-expression group were IDO2, ADORA2A, and KIR3DL1, as they showed a lower expression level in the majority of the cancer samples." (PMID 36157232, 2022). "The adenosine A2A receptor (A2AR) is a prototypical and ubiquitous class A receptor, of interest in the pharmacological treatment of specific cardiovascular disorders, immune response and wound repair, cancer, and central nervous system disorders." (PMID 34204456, 2021).
neurodegenerative disease (25 papers, 2014 to 2024). A disorder of the central nervous system characterized by gradual and progressive loss of neural tissue and neurologic function. "Convulsions trigger an elevation of extracellular adenosine and upregulate adenosine A2A receptors (A2AR), which have been associated with the control of neurodegenerative diseases." (PMID 30627646, 2018). "Several functional G-protein heterodimers (entries 1–7) and heterotrimers (entries 8–10) with other GPCRs have been observed and described for the adenosine A2A receptor (A2AR), playing significant roles in neurodegenerative diseases or drug abuse." (PMID 35057055, 2022). "The adenosine A2A receptor (A2AR) represents a potential therapeutic target for neurodegenerative diseases." (PMID 33669003, 2021). "Caffeine is a promising drug for the management of neurodegenerative diseases such as Parkinson’s disease (PD), demonstrating neuroprotective properties that have been attributed to its interaction with the basal ganglia adenosine A2A receptor (A2AR)." (PMID 28264466, 2017). "Studies in mice lacking the A2AR (adora2a) gene show reduced neuronal injury after occlusion of the middle cerebral artery, and neuroprotection in several models of neurodegenerative diseases." (PMID 31408967, 2019). "Similarly, studies in mice lacking the A2AR (adora2a) gene demonstrated reduced neuronal injury after occlusion of the middle cerebral artery and neuroprotection in several models of neurodegenerative diseases." (PMID 34360766, 2021).
infection (23 papers, 2015 to 2026). The state of being infected such as from the introduction of a foreign agent such as serum, vaccine, antigenic substance or organism. "They found that administration at the time of infection produced the best anti-inflammatory results, and that the adenosine A2A receptor is partially involved in this process." (PMID 36109476, 2023). "Spp1–integrins/Cd44 were present only in the 6-month samples, and Cxcl4–Cxcr3 and Entpd–Adora2a were present only in the 3-month samples, while Cxcl16–Cxcr6 expression gradually decreased between T cells and endothelial cells as infection progressed." (PMID 36569953, 2022). "Conversely, overexpression of ADORA2A by infection with adenovirus carrying the ADORA2A gene (Ad-A2AR) elevated ADORA2A protein levels and promoted HRMEC proliferation." (PMID 28928465, 2017). "The aim of this study was to assess if there were differences in allelic and genotypic frequencies of a loss-of-function SNP of ADORA2A (rs2298383) and a gain-of-function single nucleotide polymorphism (SNP) of P2RX7 (rs208294) in the severity of SARS-CoV-2-associated infection." (PMID 38892324, 2024). "Interestingly, among the transcripts which were specifically and highly increased in SkMCs following infection was the adenosine receptor A2A (Adora2a; 16.5-fold up-regulated)." (PMID 28775382, 2017). "Currently, no adverse reactions such as heterotopic ossification and infection of the local application of adenosine A2A receptor agonists have been found in animals." (PMID 32382539, 2020). "We could, for example, verify that expression of IL10 or SOCS3 genes is reduced during the infection or that expression of STAT4, LAMP3, ADORA2A and BIRC3 genes peaks 6 h pi." (PMID 32070192, 2020). "Furthermore, Adora2a mRNA was more abundant in neurons irrespective of infection as compared to astrocytes and fibroblasts." (PMID 28775382, 2017).
brain diseases (20 papers, 2012 to 2025). "Adenosine A2A receptor (ADORA2A), which belongs to the family of adenosine receptors that are most abundant in the brain, has been reported to contribute to neuroinflammation and synaptic and neuronal damage and is considered a biomarker of brain diseases." (PMID 36118760, 2022).
neurological disorders (19 papers, 2010 to 2026). "Therefore, one could argue that ADORA2A genetic variants are more likely to be related with the specific signs and symptoms of more than one neurological disorder." (PMID 36430879, 2022).
psychiatric disorder (14 papers, 2009 to 2024). A disorder characterized by behavioral and/or psychological abnormalities, often accompanied by physical symptoms. "Numerous evidences revealed genetic associations between the ADORA2A gene and different neurologic and developmental/psychiatric disorders." (PMID 33262686, 2020). "Additionally, ADORA2A-related long noncoding RNAs have been reported to be implicated in several processes, such as neurodegeneration and neurodevelopment, and, thus, to neurological and psychiatric disorders." (PMID 36430879, 2022). "Our earlier association studies in Polish patients with GTS have revealed a relationship between some SNPs of BTBD9, ADORA1 and ADORA2A genes and co-morbid psychiatric disorders." (PMID 32194619, 2020).
cardiovascular disease (10 papers, 2012 to 2025). "Adenosine 2 A receptor (ADORA2A) is highly expressed in vascular cells and implicated in cardiovascular disease; however, its specific role in VC pathogenesis remains unclear." (PMID 41201506, 2025).
retinopathies (4 papers, 2017 to 2024). "Taken together, these findings advance translation of ADORA2A as a therapeutic target in the treatment of proliferative retinopathies and other diseases dependent on pathological angiogenesis." (PMID 28928465, 2017). "Our study further demonstrated that endothelium-specific Adora2a deletion reduces glycolysis and pathological neovascularization in retinopathy in vivo." (PMID 28928465, 2017). "Here, we show that the adenosine A2a receptor (ADORA2A) promotes hypoxia-inducible transcription factor-1 (HIF-1)-dependent endothelial cell glycolysis, which is crucial for pathological angiogenesis in proliferative retinopathies." (PMID 28928465, 2017).
inflammation (3 papers, 2012 to 2022). Aberrant reaction of the microcirculation characterized by movement of fluid and leukocytes from the blood into extravascular tissues. "Previous studies focused on the impact of Adora2a in acute pulmonary inflammation, but these data could not provide a connection between anesthetic agents and Adora2a." (PMID 35406657, 2022).
ADORA2A also shares sentences with these, for which no sentence is quoted: Parkinson’s (16 papers); rheumatoid arthritis (12); diabetic retinopathy (7); non-small cell lung carcinoma (7); bladder cancer (6); heart disease (6); autism (5); brain injury (5); cocaine addiction (5); myocardial infarction (5); panic disorder (5); squamous carcinoma (5); temporal lobe epilepsy (5); amyloid (4); colon carcinoma (4); dyslipidemia (4); lupus (4); obsessive-compulsive disorder (4); retinal diseases (4); sarcoma (4); sleep disorder (4); tauopathy (4); type 1 diabetes (4); Vasovagal syncope (4); adenocarcinoma (3); amyotrophic lateral sclerosis (3); central nervous system disorder (3); cervical cancer (3); chronic obstructive pulmonary disease (3); dementia (3).
A further 163 diseases each share a sentence with ADORA2A in 3 papers or fewer.